MIR889 (microRNA 889)
Synonyms: hsa-mir-889; MIRN889; mir-889
Gene: MicroRNA gene on chromosome 14 (101,047,901 to 101,047,979, forward strand). Ensembl gene ENSG00000216099.
Gene Ontology:
Biological process: miRNA-mediated post-transcriptional gene silencing
Cellular component: RISC complex
Homologues: Orthologues: chimpanzee ptr-mir-889 (100% identical).